S100A9 (S100 calcium binding protein A9)
Diseases named in the same sentence as S100A9 in open-access papers (continued):
Sharing a sentence is not in itself a finding about the gene and the disease.
cancer (continued). "Moreover, some studies have shown that S100A9 could affect the viability and migration of cancer cell lines through the regulation of the Wnt/β-catenin pathway." (PMID 39596686, 2024). "Interestingly, unbiased profiling of experimental BMs with scRNAseq uncovered that, beyond a broad representation of detectable levels of S100A9 among several cancer cell clusters, a specific one characterized by its stem-like properties showed the highest levels of expression." (PMID 36652782, 2023). "In addition, S100A8/9+ myeloid cells could promote angiogenesis and exacerbate cancer through the S100a8/S100a9–Emmprin–Vegfa axis." (PMID 36420271, 2022). "In addition to the impact on cancer development, the induction of S100A9 by hypoxia may play an important role in ischemic events." (PMID 36041055, 2022). "However, it remains controversial in the clinical setting whether the increased expression of S100A9 predicts a good or poor prognosis of cancer patients." (PMID 35304461, 2022). "Finally, stratifying patients regarding their HPV/S100A8/S100A9/CD15/CD147 profile may help identify patients with progressing cancer and tailor immunotherapeutic treatment strategies." (PMID 36303837, 2022). "In addition, S100A9 is deeply involved in cancer development and malignancy transformation." (PMID 34045609, 2021). "Moreover, anti-inflammatory TAMs induce S100A8 and S100A9 expression on HCC cancer cells, release CCL22 and epidermal growth factor (EGF) to recruit Treg cells, and promote migration of tumor cells, altogether contributing to HCC malignancy and liver metastasis." (PMID 31611871, 2019). "Inhibition of S100A8 and S100A9 activity may have significant implications in cancer chemotherapy." (PMID 29955397, 2018). "Overexpression of S100A9 in cultured embryonic stem cells or transgenic mice led to inhibition of differentiation of dendritic cells and macrophages and induced accumulation of myeloid-derived suppressor cells, one of the major immunological abnormalities in cancer." (PMID 29416786, 2018). "Therefore, the actions of S100A9 through MAPK signals could be depend on the different types of cancer cells." (PMID 27020242, 2016). "S100A8 and S100A9, members of the S100 proteins, are small calcium-binding proteins that are highly expressed in neutrophil and monocyte cytosol and are found to be overexpressed during inflammatory conditions and in some types of cancer such as pancreatic, colorectal, and gastric cancer." (PMID 26273651, 2015). "S100A9 may also be involved in cancer progression by separate mechanisms." (PMID 23667563, 2013). "As the enhanced level of S100A8 and S100A9 proteins is a characteristic feature of numerous inflammatory, cancers and degenerative conditions taking place in different tissues and organs, they may effectively contribute to the disease pathologies also via amyloid depositions." (PMID 22489132, 2012). "For example, S100A8 and S100A9 activate mitogen-activated protein kinases(MAPK) and nuclear factor-kappaB(NF-κB) signaling, promoting migration and inflammation in cancer cells." (PMID 41404073, 2025). "Mφ can activate the NF‐κB signaling pathway by secreting factors such as S100A9 and IL-6, which promotes the stemness of HCC cells and the self-renewal of cancer stem cells (CSCs), thus providing a pro‐tumorigenic niche for early HCC." (PMID 40621461, 2025). "In conclusion, S100A9 is capable of binding to certain receptors, including TLR4, RAGE, and MCAM, through which it can trigger specific pathways which can then stimulate cancer cell proliferation, metastases, and malignancy." (PMID 41009692, 2025). "Knocking out Gal-7 and S100A9 increases MMP-9 expression and activates the PI3K/Akt signaling pathway, enhancing cancer cell proliferation." (PMID 40134029, 2025). "Surprisingly, the spread of cancer cells in M1 patients exhibited highly significant levels of HMGB1, HSP90, and S100A9 when compared with M0 patients." (PMID 39768997, 2024).
cancer (continued). "In vitro experiments revealed that stress hormones downregulated HDC expression, consequently promoting cancer cell proliferation, migration, and invasion via the IL-6/STAT3/S100A9 pathway." (PMID 39720595, 2024). "The results showed that FLOR2+ macrophage proportion was higher in responders of SKCM, while this of S100A9+ macrophages was lower, which was inconsistent with the results of all cancer and TNBC, suggesting heterogeneity of cancers." (PMID 38569519, 2024). "Our study found that S100A9 was also significantly up-regulated in GBM tissues, mainly expressed in monocytes and macrophages, and also expressed in malignant tumor cells." (PMID 39137310, 2024). "Receptors of S100A9, including TLR4, RAGE, CD147, MCAM and NPTN are expressed in multiple cell types, such as cancer cells, MDSCs, macrophages and NK cells." (PMID 38713229, 2024). "A role of S100A8, S100A9 or heterodimer S100A8/A9 in the development and function of suppressive MDSCs in cancer was discovered and reported in 2008 by two separate groups." (PMID 39497822, 2024). "For instance, B2M, SLPI, BST2, GAPDH, S100A8, S100A9, and HMGB1, despite their beneficial roles in various infections, they contribute to cancer cell proliferation, invasiveness, reduced survival, and increased disease severity across different cancers." (PMID 38589404, 2024). "This activation enhances cancer cell migration and invasion through EMT and also activates the proto-oncogene MYC via the ROS/S100A9/MYC signaling axis, promoting tumorigenesis." (PMID 39457673, 2024). "The mean concentration of HMGB1 among M0 and M1 cancer patients was 3.16 ± 0.29 and 3.44 ± 0.28 ng/mL; for HSP90, it was 16.83 ± 10.48 and 28.46 ± 7.36 ng/mL; and for S100A9, it was 5.04 ± 1.26 and 6.49 ± 2.24 ng/m, respectively." (PMID 39768997, 2024). "Regarding area under the curve (AUC), HSP90 was the best at distinguishing the metastasis status of cancer patients, followed by HMGB1 and S100A9." (PMID 39768997, 2024). "Previous literature suggests that S100A9 is involved in various functions within TME, including cancer cell migration, neutrophil recruitment, and escape from immune surveillance by cancer cells via TGFβ activation." (PMID 39516397, 2023). "Due to the characteristics of participating in the recurrence and metastasis of a variety of cancers, Fn-1, S100A8, S100A9, and MMP9 were regarded as the main components of the formation of the pre-metastatic microenvironment." (PMID 37330523, 2023). "Second, S100A9 is known to be expressed by myeloid-derived suppressor cells (MDSC) and promotes polarisation of M2 macrophages present in the TME of many cancers including CRC." (PMID 39516397, 2023). "Cancer-promoting genes including MMP9, S100A8, S100A9, PORK2, and TGF-β1 were identified as high-expression DEGs in NE-1." (PMID 37333017, 2023). "In contrast, conditioned media and cytokines derived from cancer cells upregulated the expression of S100A8 and S100A9 in monocytes." (PMID 35651786, 2022). "A heterodimer complex of the S100A8 and S100A9 proteins, S100A8/A9 functions as a strong chemoattractant, growth factor, and immune suppressor, both promoting the cancer milieu at the cancer-onset site and cultivating remote, premetastatic cancer sites." (PMID 36142212, 2022). "After confirming the correlation of CD55 and S100A9 in H2030-BrM brain metastases, sorted CD55+ and CD55− cancer cells were subjected to oncosphere assays." (PMID 35411077, 2022). "S100A9, which is an immunosuppressive TAM marker, is related to the shorter survival period of cancer patients and adverse reactions to immunotherapy." (PMID 35693827, 2022). "S100A8 and S100A9 are constitutively expressed in neutrophils, MDSC and other cell types that promote progression of cancer." (PMID 35655772, 2022). "Concurrently, the protein level of S100A9, SLC22A15, and TRIM54 was found to be much higher in the cancer tissues or the cells around the blood sinus compared to the normal tissues." (PMID 36120553, 2022).
cancer (continued). "These include: CDH1, MUC1, THBS4, and MSLN for PEs related to cancer; ADA2, CXCL10, and WARS for TB-PEs; CRP, S100A9, and VIM for parapneumonic PEs; and C9, LDHA, HPX, LDHB, and C3 for benign-PEs." (PMID 35197508, 2022). "S100A8 and S100A9 are highly expressed in MDSC and are reported to regulate MDSC activity to promote immunosuppression in cancer." (PMID 35655772, 2022). "The interaction between S100A9 and EMMPRIN induced cdc42 activation promoting filopodia formation, migration, and cancer cell polarity." (PMID 33567747, 2021). "In particular, S100A8, S100A9 and S100A12 are highly abundant proteins released by neutrophils and have been identified as important biomarkers in many inflammatory diseases and cancers." (PMID 33468080, 2021). "Another therapeutic option in cancer is targeting the ability of NETs to secrete the Ca2+-binding proteins S100A8 and S100A9." (PMID 34503307, 2021). "From these data, we selected potential biomarkers of cancer including six upregulated proteins (RNF213, CTSG, PGLYRP1, RPL8, S100A8, S100A9) and two downregulated proteins (GPX1, TNS1)." (PMID 34361002, 2021). "Subsequently, seven common genes, including FOSL1, S100A9, CXCL12, ID2, PRS6KA3, AREG, and DUSP6, have been used as the target biomarkers for cancer diagnosis and therapy." (PMID 34490085, 2021). "Because most of the S100 proteins have been considered as EMT facilitators in certain carcinoma cell lines, the present study showed that HE of AHNAK2 had a significantly higher proportion of S100A4, S100A8, and S100A9 expressions." (PMID 33918555, 2021). "These cells were recruited to tumors by cancer cell-derived CXCL1/2 chemokines, and served as a major source for the pro-inflammatory proteins S100A8 and S100A9." (PMID 33585241, 2020). "Because suspension and dense culture leads to cell apoptosis, even for cancer cells, we next explore the function of S100A8/S100A9 in suspended and dense SCC cells." (PMID 31208368, 2019). "For example, over-expression of CXCL1 and CXCL2 favors cancer cell survival in metastatic sites through the induction of S100A8 and S100A9 secretion from CD11b+Gr1+cells." (PMID 28429725, 2017). "In tissue culture and in the liver colonies derived from cancer cells with knockdown of S100A8 and S100A9, MMP2 and MMP9 expression was decreased, consistent with the reduction in migration and invasion." (PMID 27086923, 2016). "Downregulation of S100A8 and S100A9 was further accompanied by decreased MMP2 and MMP9 expression in cancer cells, both in culture and in metastatic liver colonies." (PMID 27086923, 2016). "S100A8 and S100A9 knockdown significantly decreased MMP2 and MMP9 protein levels in the cancer cells." (PMID 27086923, 2016). "qPCR analysis of a number of reported miR196a targets in other cancers, KRT5, ANXA1, S100A9 and HOXC8, was conducted." (PMID 25860510, 2015). "By our analysis, we have identified novel regions of allelic imbalance that contain several cancer related genes such as CHD1L and S100A9 at locus 1q21.1; and CENPF and ESRRG at locus 1q32-q42." (PMID 26314549, 2015). "S100A8 and S100A9 were upregulated in RCC patients compared with patients with benign kidney lesions, other urological tumors or non-cancer patients." (PMID 25673070, 2015). "Several studies have demonstrated that S100A9 protein can promote M2 polarization of macrophages and induce immunosuppressive TME by recruiting and accumulating of myeloid-derived suppressor cells in cancer." (PMID 40900789, 2025). "In cervical squamous carcinoma, the expression levels of both Gal-7 and S100A9 are decreased, showing a negative correlation with cancer staging and lymph node metastasis." (PMID 40134029, 2025). "S100a8 and S100a9, secreted by adipocytes, preadipocytes, or neutrophils, have been identified as key genes affecting lipid metabolism, such as FFA (18:3), and in turn, cancer development in aged animals." (PMID 39796176, 2025).
cancer (continued). "In this study, we asked if Paquinimod, for which direct binding to S100A9 protein and TLR4 receptor inhibition activity was first published, could impact on suppressive myeloid cells and achieve anti-cancer efficacy." (PMID 39497822, 2024). "Also, S100A8 and S100A9 were down-regulated after CD36 knockdown, which are classical ligands related to cancer aggressiveness." (PMID 37207149, 2023). "To elucidate whether the elevated S100a9 signaling in cancers could increase MDSC accumulation in mice, we generated doxycycline (DOX) S100a9-inducible B477 cells (Brca1-WT-Dox) and G600 cells (Brca1-MT-Dox)." (PMID 35304461, 2022). "Complementary, the significant reduction in brain metastases upon S100A9 knockdown in cancer cells did not correlate with changes in the number of infiltrating neutrophils." (PMID 35411077, 2022). "However, S100A9, together with S100A8, were the two genes with the most variable expression pattern among cancer cells." (PMID 35411077, 2022). "Proteins S100A8, S100A9, or hetero-oligomer S100A8/A9 might also promote cancer cells migration and dissemination through regulation of tumoral microenvironment." (PMID 33801279, 2021). "Cancer-related genes HDC, GATA2, and SLC45A3 were downregulated and S100A9 was upregulated by CUMS." (PMID 34650925, 2021). "For example, since GLI3 negatively regulates S100A9 in OSCC cancer stem cells and this has been shown to induce cell death in cancer cell lines, targeted depletion of GLI3 in OSCC might be an effective strategy in the treatment of OSCC." (PMID 32245491, 2020). "Although researchers focused on the roles of S100A8/S100A9 in inflammatory cells currently, there is also growing evidence for important roles of both proteins in non-myeloid cells, such as skin cells and cancer cells." (PMID 31208368, 2019). "Given the correlation of S100A9 with HBV infection and previous finding of significance of S100A9 in HCC, S100A9 could be an important cancer promoter in HBV-related carcinogenesis and be a therapeutic target for patients with HBV-related HCC." (PMID 29615081, 2018). "In contrast, conditioned media from naIve monocytes/macrophages and granulocytes isolated from normal livers did not alter S100a8 and S100a9 mRNA expression in the cancer cells." (PMID 27086923, 2016). "When we constructed S100A8/A9-positive transfectants in S100A8/A9-negative (no S100A8/A9 protein complex) human carcinoma cells, transfection of S100A9 without S100A8 was unsuccessful and cells died." (PMID 26883112, 2016). "We continued with another cancer-related DAMP reported to be a TLR4 ligand, the S100A9 protein." (PMID 26392082, 2015). "To confirm our hypothesis that the inflammation seen in fibrotic NASH patients might lead the way to cancer, we investigated the level of the two calgranulins, S100A8 and S100A9, in the serum of patients affected by NASH." (PMID 26273651, 2015). "Overall, our findings support the hypothesis that S100A8, S100A9 and NT-S100A8 are Janus-faced molecules that can have pro- and anti-cancer effects, depending on the cellular context." (PMID 24670043, 2014). "To begin to address mechanisms that might be responsible for this HV-68-exacerbated cancer, we questioned whether virus-induced increases in S100A8/S100A9 levels might induce increased MDSCs in vivo." (PMID 22946998, 2012). "Fourth, when the HCC cases were categorized according to cancer pathological grade, high mRNA expression of S100A7 in pathological grades II and III correlated with shorter OS, as did high expression of S100A9 in pathological grade II and of S100A10 in pathological grade III." (PMID 39128058, 2024). "In addition to transcription factors, in AML samples, we identified the upregulation of genes that were reported to accelerate leukaemogenesis, including S100A8, S100A9, and RPS26, and the downregulation of genes related to cancer control and defence, such as XIST, GIMAP7, NKG7, and GNLY." (PMID 37615858, 2024).
cancer (continued). "Furthermore, single-cell sequencing data further confirmed that the S100A9 in the model had differential expression between the two types of cancer, and S100A9 in invasive BCa was significantly higher than that in non-invasive BCa." (PMID 37691944, 2023). "Further supporting the importance of S100 specific members in cell motility and cancer metastasis, matrix metalloproteinase (MMP) expression/activity and degradation of the extra-cellular matrix (ECM) is also under the control of S100 proteins such as S100A4, S100A8, S100A9, S100A10 and S100A14." (PMID 36232334, 2022). "Six of these proteins had a higher abundance in cancer patients than in healthy controls (RNF213/ring finger protein 213; CTSG/cathepsin G; PGLYRP1/peptidoglycan recognition protein 1; RPL8/ribosomal protein L8; S100A8/S100 calcium binding protein A8; S100A9/S100 calcium binding protein A9)." (PMID 34361002, 2021). "In our study, gene expression analyses show that S100A2, S100A11, and S100P expression levels in CRC tissues are significantly higher than those in noncancerous tissues, and S100A3 and S100A9 mRNAs are highly expressed in cancer tissues compared with normal tissue controls." (PMID 33294444, 2020). "Hence, exposure of cancer and endothelial cells to 0.5-1μM concentrations of tasquinimod will produce intracellular levels of 2 to 3 μM or more than twenty-fold higher than needed to bind and thus also inhibit HDAC4 and S100A9." (PMID 25193858, 2014). "Overall, we validated the consistency of up-regulation of the four proteins (COL12A1, THBS2, S100A8, and S100A9) was only observed in CRC but not in other cancer types; and the four proteins could achieve good performance in the diagnosis of CRC, but not other cancer types." (PMID 38302471, 2024). "The observed underexpression of S100A9 in patients with non-seminomatous TGCTs when compared to those with seminomatous TGCTs may be due to the different cellular response related to different types of cancer." (PMID 32650378, 2020). "In human primary tumors originating from tissues that normally express little or no S100A8 and S100A9 protein, such as skin, breast, thyroid, liver, gastric mucosa, prostate, ovary, bladder, and lung, S100A8/A9 levels are often elevated in association with tumorigenesis and cancer progression." (PMID 26883112, 2016). "A limitation of this study is that tasquinimod, the inhibitor for S100A9, and AMD3465, which blocks the cell surface binding of CXCL12 to CXCR4, are currently under clinical trial and has been not approved for cancer therapy yet." (PMID 35304461, 2022). "KB cells were used as an in vitro model for gain-of-function study since this carcinoma line fails to express S100A8 and S100A9 mRNA and protein." (PMID 23874958, 2013). "The mechanisms mediating S100A8 and S100A9 regulation of MMP2 and MMP9 expression in cancer cells are not yet known but may involve their calcium-binding activity." (PMID 27086923, 2016). "Although the S100A9 inhibitor paquinimod has been extensively studied in inflammation, it is unknown if S100A9 inhibitors, such as paquinimod, are effective in TAM polarization, as no such data exist for cancers to date." (PMID 35327584, 2022).